SLC4A1 (solute carrier family 4 member 1 (Diego blood group))
Description:
Functions both as a transporter that mediates electroneutral anion exchange across the cell membrane and as a structural protein. Component of the ankyrin-1 complex of the erythrocyte membrane; required for normal flexibility and stability of the erythrocyte membrane and for normal erythrocyte shape via the interactions of its cytoplasmic domain with cytoskeletal proteins, glycolytic enzymes, and hemoglobin. Functions as a transporter that mediates the 1:1 exchange of inorganic anions across the erythrocyte membrane. Mediates chloride-bicarbonate exchange in the kidney, and is required for normal acidification of the urine. (Microbial infection) Acts as a receptor for P.falciparum (isolate 3D7) MSP9 and thus, facilitates merozoite invasion of erythrocytes. Acts as a receptor for P.falciparum (isolate 3D7) MSP1 and thus, facilitates merozoite invasion of erythrocytes.
Synonyms: CD233; AE1; DI; EPB3; RTA1A; FR; SW; WR; EMPB3; BND3; CHC; SAO; SPH4; WD; WD1
Tractability: Small molecule: a structure with a bound ligand is known; it has a high-quality binding pocket. Antibody: UniProt places it where antibodies can reach, with high confidence; its Gene Ontology location is reachable by antibodies, with high confidence; UniProt predicts a signal peptide or a membrane-spanning region. PROTAC: ubiquitination databases record sites on it; its protein half-life has been measured.
Gene: Protein-coding gene on chromosome 17 (44,248,390 to 44,268,141, reverse strand). Ensembl gene ENSG00000004939.
Subcellular location: Cell membrane; Basolateral cell membrane
Pathways (Reactome):
Transport of small molecules: Bicarbonate transporters; Erythrocytes take up carbon dioxide and release oxygen; Erythrocytes take up oxygen and release carbon dioxide
Disease: Defective SLC4A1 causes hereditary spherocytosis type 4 (HSP4), distal renal tubular acidosis (dRTA) and dRTA with hemolytic anemia (dRTA-HA)
Gene Ontology:
Molecular function: ankyrin binding; bicarbonate transmembrane transporter activity; chloride:bicarbonate antiporter activity; protein binding; protein homodimerization activity; solute:inorganic anion antiporter activity; chloride transmembrane transporter activity; monoatomic anion transmembrane transporter activity; protein-membrane adaptor activity; cytoskeletal protein binding; hemoglobin binding
Biological process: bicarbonate transport; chloride transmembrane transport; chloride transport; intracellular monoatomic ion homeostasis; monoatomic anion transport; regulation of intracellular pH
Cellular component: ankyrin-1 complex; basolateral plasma membrane; blood microparticle; cortical cytoskeleton; extracellular exosome; plasma membrane; membrane; Z disc; cytoplasm; cytoplasmic side of plasma membrane
Genetic constraint (gnomAD): Loss-of-function variants: 29 observed, 97.11 expected, observed/expected ratio (o/e) 0.3, 90% interval 0.22 to 0.41. The upper end of that interval is the gene's LOEUF score, 0.41, which puts it in group 1 of 6, group 1 being the genes least tolerant of losing a copy. Missense variants: 963 observed, 1,231.8 expected, observed/expected ratio (o/e) 0.78, 90% interval 0.74 to 0.82. Synonymous variants: 469 observed, 518.3 expected, observed/expected ratio (o/e) 0.9, 90% interval 0.84 to 0.98.
Homologues: Orthologues: chimpanzee SLC4A1 (99% identical), macaque SLC4A1 (95% identical), dog SLC4A1 (85% identical), mouse Slc4a1 (82% identical), rat Slc4a1 (80% identical), guinea pig SLC4A1 (79% identical), pig SLC4A1 (77% identical), rabbit SLC4A1 (76% identical), tropical clawed frog slc4a1 (62% identical), zebrafish slc4a1a (51% identical), zebrafish slc4a1b (51% identical), Drosophila melanogaster Ae2 (43% identical), and 3 more. Paralogues in human: SLC4A2 (59% identical), SLC4A3 (56% identical), SLC4A4 (37% identical), SLC4A7 (37% identical), SLC4A5 (37% identical), SLC4A10 (37% identical), SLC4A8 (36% identical), SLC4A9 (34% identical), SLC4A11 (22% identical).
Diseases named in the same sentence as SLC4A1 in open-access papers:
SLC4A1 is named in the same sentence as 149 diseases in open-access papers, as found by Europe PMC text mining. Sharing a sentence is not in itself a finding about the gene and the disease. The quoted sentences say what the papers report.
hereditary spherocytosis (25 papers, 2009 to 2026). Hereditary spherocytosis is a congenital hemolytic anemia with a wide clinical spectrum (from symptom-free carriers to severe hemolysis) characterized by anemia, variable jaundice, splenomegaly and cholelithiasis. "Exome sequencing revealed a heterozygous mutation in SLC4A1 gene (c.1239_1241del), which is associated with hereditary spherocytosis." (PMID 42058779, 2026). "We reported 2 Taiwanese families, 1 was hereditary spherocytosis affected by a heterozygous mutation with c.166A > G (p.Lys56Glu) in SLC4A1 (Band 3 protein), and the other was hereditary elliptocytosis caused by a novel heterozygous SPTA1 gene mutation, c." (PMID 36705355, 2023). "The newly discovered variant p.G720W of the SLC4A1 gene is most likely the cause of clinical symptoms typical of hereditary spherocytosis." (PMID 36979763, 2023). "According to the literature, in cases of hereditary spherocytosis correlated with SLC4A1 gene mutations, a 20–35% loss of AE1 is usually observed." (PMID 36979763, 2023). "This is, however, due to the fact that SLC9A3 is also a cystic fibrosis modifier gene, SLC4A1 is also associated with spherocytosis, and SLC6A19 also causes Hartnup disease, all of which are comparatively frequent conditions." (PMID 35456490, 2022). "Then, the method was tested on 10 patients with different genetic mutations causing hereditary spherocytosis (SLC4A1, ANK1)." (PMID 33983926, 2021). "At a correlation cut-off of 0.8, a coexpression subnetwork of 26 GWAS-associated genes was centered on three known Mendelian genes causative for spherocytosis (SLC4A1, EPB42) and congenital anemia (KLF1)." (PMID 32888494, 2020). "SLC4A1 mutations cause destabilization of the erythrocyte’s membrane leading to hereditary spherocytosis." (PMID 30836997, 2019). "Specific SLC4A1 mutations cause dRTA associated with hemolytic anemia or spherocytosis since the AE1/band 3 is also crucial for erythrocyte integrity." (PMID 22966473, 2012). "Many mutations in this gene had been known in human, and it was reported to be that over expression of SLC4A1 could lead to some diseases like hereditary spherocytosis caused by destabilization of cell membrane, and inherited distal renal tubular acidosis." (PMID 34633991, 2021). "The same female-specific associations are observed around the gene SLC4A1, which encodes for erythrocyte band 3 protein that plays a pivotal role in regulating anion transport across membranes, and for which mutations are associated with hereditary spherocytosis and the Diego blood group." (PMID 35321643, 2022). "Particularly interesting for us were five genes associated with clinical phenotypes of hereditary spherocytosis (SPTA1, SPTA, SLC4A1, ANK1, and EPB42)." (PMID 36979763, 2023). "SPH1 (Spherocytosis, type 1), SPH2 (Spherocytosis, type 2), SPH3 (Spherocytosis, type 3), SPH4 (Spherocytosis, type 4), SPH5 (Spherocytosis, type 5) are caused by ANK1, SPTB, SPTA1, SLC4A1, and EPB42 gene mutations, respectively." (PMID 37795245, 2023). "Thirteen variants were identified in five hereditary spherocytosis-related genes (six in ANK1 [SPH1]; four in SPTB [SPH2]; and one in each of SPTA1 [SPH3], SLC4A1 [SPH4], and EPB42 [SPH5])." (PMID 35022413, 2022).
hereditary spherocytosis (continued). "SLC4A1-induced spherocytosis usually shows dominant inheritance, which fits with the transmission in the family." (PMID 36231035, 2022). "Five genes are associated with spherocytosis, including SPTA1, SPTB, ANK1, SLC4A1, and EPB42, which are involved in the interplay between the erythrocyte membrane and the lipid bilayer." (PMID 34481427, 2021). "Hereditary spherocytosis and hereditary dRTA are associated with mutations in the SLC4A1 gene encoding the AE1." (PMID 34481427, 2021). "The characteristics that EPB42 and SLC4A1 was over expressed in hereditary spherocytosis was consistent with the hematological features of PMF that the presence of large amount of erythrocyte in the peripheral blood cell smear." (PMID 34633991, 2021). "While SLC4A1 could potentially be a drug target for conditions such as hereditary spherocytosis, more research is needed." (PMID 37845713, 2023). "We reported two Taiwanese families, one was hereditary spherocytosis affected by a heterozygous mutation with c.166A > G (p.Lys56Glu) in SLC4A1, and the other was hereditary elliptocytosis caused by a novel heterozygous SPTA1 gene mutation, c." (PMID 36705355, 2023). "SLC4A1, due to its crucial function in red blood cell physiology and its link to hereditary spherocytosis, may serve as a potential blood transcriptional biomarker for this condition." (PMID 37845713, 2023). "Hereditary spherocytosis (HS) is an inherited disorder characterized by anemia, splenomegaly, and spherical-shaped erythrocytes, caused by mutations in erythrocyte membrane Protein Genes (ANK1, SPTB, SLC4A1, SPTA1, and EPB42)." (PMID 33014018, 2020). "We analyzed the SLC4A1 gene in three Mexican patients with Hereditary Spherocytosis (HS)." (PMID 21637597, 2010). "The SLC4A1 gene drives the formation of an anion exchanger that modulates intracellular and extracellular pH by orchestrating the exchange of chloride, bicarbonate, and carbonate anions across the cell membrane, an integral process affected in conditions such as hereditary spherocytosis." (PMID 37845713, 2023). "The measurement of band 3 (AE1, SLC4A1, CD233) content of red cells by eosin-5- maleimide (EMA) staining is swiftly replacing conventional osmotic fragility (OF) test as a tool for laboratory confirmation of hereditary spherocytosis across the globe." (PMID 32636758, 2020). "However, genetic testing by NGS showed no mutations in ANK1, EPB42, SLC4A1, SPTA1, or SBTB genes in this and an additional two patients, thus ruling out hereditary spherocytosis in all studied cases." (PMID 35681698, 2022).
distal renal tubular acidosis (22 papers, 2012 to 2026). A kidney disorder of impaired net acid secretion by the distal tubule characterized by hyperchloremic metabolic acidosis. "The decreased abundance at the plasma membrane and altered recycling provide a possible physiological mechanism of distal renal tubular acidosis in patients carrying SLC4A1 mutations." (PMID 36776909, 2023). "SLC4A1 genetic variants are associated with hereditary spherocytosis (HS), stomatocytosis (HSt), or distal renal tubular acidosis (dRTA)." (PMID 34669510, 2021). "SLC4A1 is distributed mainly in erythrocytes, intercalated cells of the renal collecting duct, heart, and colon, and has an association with a series of diseases such as hemolytic anemia and distal renal tubular acidosis." (PMID 36077090, 2022). "Previous reports suggested that the abnormal function of SLC4A1 was a risk factor for idiopathic calcium nephrolithiasis, and the mutations of it might cause distal renal tubular acidosis, which also promoted recurrent renal stone formation." (PMID 29392139, 2017). "Pathogenic variants in the B1 and a4 subunits of H+-ATPase (ATP6V1B1, ATP6V0A4) and in AE1 (SLC4A1) have been identified as the cause of distal renal tubular acidosis (dRTA) almost two decades ago." (PMID 38448728, 2024). "Mutations in the SLC4A1 gene encoding the anion exchanger 1 (AE1) can cause distal renal tubular acidosis (dRTA), a disease often due to mis-trafficking of the mutant protein." (PMID 23460825, 2013). "Rare homozygous mutations of the SLC4A1 gene have been revealed, including the Coimbra mutation (Val488Met), which causes an extremely severe form of HS, associated with impaired renal anion metabolism and kidney damage (distal renal tubular acidosis, DRTA)." (PMID 40008208, 2025). "Familial distal renal tubular acidosis (dRTA) associated with mutations of solute carrier family 4 membrane − 1 (SLC4A1) gene could co-exist with red cell membrane abnormality, Southeast Asian ovalocytosis (SAO)." (PMID 32758154, 2020). "The genetic and clinical characteristics of patients with distal renal tubular acidosis (dRTA) caused by SLC4A1 mutations have not been systematically recorded before." (PMID 36776909, 2023). "Moreover, SLC4A1 and SLC6A19 are part of the panel because they are associated with distal renal tubular acidosis (Orphacode 93608), and iminoglycinuria (Orphacode 42062), respectively, two co-morbidities of nephrolithiasis." (PMID 35456490, 2022). "For instance, SLC4A1 a causal gene for distal renal tubular acidosis or RBC abnormalities and CKD has recently been identified in 30–80% of primary dRTA patients." (PMID 36314741, 2022). "Mutations of the Cl2/HCO3·2 exchanger AE1, encoded by SLC4A1 which is expressed in red blood cells and in type A intercalated cells of the renal collecting tubule, may be responsible for distal renal tubular acidosis (dRTA), with or without haemolytic anemia." (PMID 31731473, 2019).
gastric cancer (9 papers, 2010 to 2022). A primary or metastatic malignant neoplasm involving the stomach. "SLC4A1, which is normally only expressed at detectable protein levels in erythrocytes, was found to be markedly upregulated in gastric cancer cells and colorectal cancer (CRC) cells, and its expression to correlate with cancer progression." (PMID 24795638, 2014). "Knockdown of SLC4A1 reduced tumor progression in two different mouse models of gastric cancer, a xenograft model and chemical induction in conjunction with H. pylori." (PMID 24795638, 2014). "Furthermore, gastrin was found to reduce SLC4A1 expression in gastric cancer cells by eliciting its protein degradation." (PMID 24795638, 2014). "Interestingly, the upregulation of SLC4A1 in gastric cancer was recently found to be dependent on aberrant regulation by miR-24, which normally silences SLC4A1 protein expression by interaction with the 3′ untranslated region (UTR) of the gene." (PMID 24795638, 2014).
ovalocytosis (9 papers, 2018 to 2023). "Of the 3 heterozygotes with a normal copy number of α globin genes one had co-inherited a mutation in the SPTA1 gene associated with HS, and another had co-inherited the SLC4A1 variant for south Asian Ovalocytosis." (PMID 31300739, 2019). "We discovered that the patient who had AR dRTA coexisting with mild hemolytic anemia carried a novel compound heterozygous SLC4A1 mutations containing c.1199_1225del (p.Ala400_Ala408del), resulting in Southeast Asian ovalocytosis (SAO), and c.1331C > A (p.Thr444Asn)." (PMID 36320073, 2022). "Thus, defects of the SLC4A1 gene can cause morphological changes of red blood cells, including ovalocytosis and spherocytosis or dRTA condition." (PMID 36320073, 2022). "We previously reported on the only known case of homozygous Southeast Asian Ovalocytosis (SAO), a condition caused by a mutation in SLC4A1 the gene encoding erythrocyte anion exchanger 1 (AE1, band 3)." (PMID 32411010, 2020). "Similarly, Southeast Asian ovalocytosis (SAO), which is due to a heterozygous 27 bp deletion in the SLC4A1 gene (encoding the band 3 protein), is associated with protection from cerebral P. falciparum malaria." (PMID 30279439, 2018).
southeast Asian ovalocytosis (9 papers, 2017 to 2025). Southeast Asian ovalocytosis (SAO) is a rare hereditary red cell membrane defect characterized by the presence of oval-shaped erythrocytes and with most patients being asymptomatic or occasionally manifesting with mild symptoms such as pallor, jaundice, anemia and gallstones. "Familial dRTA and an inherited erythrocyte disorder ‘Southeast Asian Ovalocytosis’ (SAO), both caused by mutations in the solute carrier family 4 membrane − 1 (SLC4A1) gene, may be co-inherited in trans resulting in dRTA." (PMID 32758154, 2020). "Some SLC4A1 substitutions results in preeclampsia, renal tubular acidosis, and Southeast Asian Ovalocytosis (SAO), and as far as the present genetic marker is concerned, the Dib and Dia antigens are highly involved in cases of hemolytic disease of the newborn (HDNB)." (PMID 30143806, 2019). "The malaria-protective trait known as Southeast Asian ovalocytosis (SAO) is underpinned by a 27-bp in-frame deletion in SLC4A1 (codons 400–408)." (PMID 41450567, 2025).
COVID-19 (6 papers, 2020 to 2024). A disease caused by infection with severe acute respiratory syndrome coronavirus 2. "SLC4A1, a major integral glycoprotein on the erythrocyte membrane that is involved in carbon dioxide transport in the lung and chloride-bicarbonate exchange in the kidney, was also upregulated in the COVID-19 lung tissue." (PMID 33060566, 2020).
malaria (5 papers, 2012 to 2025). Malaria is a serious and sometimes fatal disease caused by a parasite that commonly infects a certain type of mosquito which feeds on humans. "The SLC4A1 gene encodes the erythroid anion exchanger Band 3, a protein critically involved in erythrocyte physiology and malaria pathogenesis." (PMID 41450567, 2025). "Nevertheless, alleles of different well-known genes that are likely to have undergone selection by malaria have been identified using this approach, such as GYPC (glycophorin C), ABO (ABO blood group), and SLC4A1 (erythrocyte membrane protein band)." (PMID 24005574, 2014).
renal tubular acidosis (4 papers, 2014 to 2024). A group of genetic disorders of the kidney tubules characterized by the accumulation of metabolically produced acids with elevated plasma chloride, hyperchloremic metabolic acidosis. "For example, the disease node labelled Renal Tubular Acidosis was linked to one cytokine, three proteins and 12 RNA despite that this disease was only related to two known RNA (SLC4A1, CA2) in this network." (PMID 34883510, 2022). "SLC4A1 shares phenotypes with CA2, including periodic paralysis (HP:0003768), renal tubular acidosis (HP:0001947) and hypokalemia (HP:0002900) and is also biochemically related to CA2 by physical interactions." (PMID 25420641, 2014).
breast carcinoma (3 papers, 2010 to 2024). "However, some general trends are observed across all breast cancer subtypes: SLC4A1, SLC4A4, SLC26A3, and SLC26A4 seem to be consistently down-regulated, while SLC4A5 is up-regulated, in all breast cancer subtypes compared to normal breast tissue." (PMID 24795638, 2014).
diabetes mellitus (3 papers, 2022 to 2024). A metabolic disorder characterized by abnormally high blood sugar levels due to diminished production of insulin or insulin resistance/desensitization. "Instead, in ex vivo or in vitro models of inflammation, diabetes mellitus and ageing, the SLC4A1 ion transport was found accelerated." (PMID 35143116, 2022). "In particular for ESKD, we have identified three genes that might help identify people with a higher risk of developing this more aggressive form of kidney disease, both in the overall population (NUP210 and SLC4A1) and in people with diabetes (SURF1)." (PMID 38858654, 2024). "Furthermore, SLC4A1 was also relevant to lipid peroxidation and the reduction of the GSH/GSSG ratio in diabetes mellitus." (PMID 36077090, 2022).